RNU6-1121P (RNA, U6 small nuclear 1121, pseudogene)
Gene: Small nuclear RNA gene on chromosome 10 (114,969,460 to 114,969,568, reverse strand). Ensembl gene ENSG00000252611.
Homologues: Orthologues: chimpanzee U6 (96% identical), macaque U6 (94% identical), rat LOC120103232 (54% identical), guinea pig U6 (50% identical), mouse Gm55831 (42% identical). Paralogues in human: RNU6-921P (72% identical), RNU6-274P (72% identical), RNU6-403P (72% identical), RNU6-73P (72% identical), RNU6-1005P (71% identical), RNU6-16P (71% identical), RNU6-20P (71% identical), RNU6-28P (71% identical), RNU6-35P (71% identical), RNU6-854P (71% identical), RNU6-1036P (70% identical), RNU6-1124P (70% identical), and 1282 more.